RBAK-RBAKDN (RBAK-RBAKDN readthrough)
Synonyms: RBAK-LOC389458
Gene: Protein-coding gene on chromosome 7 (4,983,718 to 5,073,221, forward strand). Ensembl gene ENSG00000272968.
Genetic constraint (gnomAD): Loss-of-function variants: 17 observed, 23.62 expected, observed/expected ratio (o/e) 0.72, 90% interval 0.49 to 1.08. The upper end of that interval is the gene's LOEUF score, 1.08, which puts it in group 4 of 6, group 1 being the genes least tolerant of losing a copy. Missense variants: 337 observed, 304.34 expected, observed/expected ratio (o/e) 1.11, 90% interval 1.01 to 1.21. Synonymous variants: 141 observed, 116.72 expected, observed/expected ratio (o/e) 1.21, 90% interval 1.05 to 1.39.